MIR1185-2 (microRNA 1185-2)
Synonyms: hsa-mir-1185-2; MIRN1185-2; mir-1185-2
Gene: MicroRNA gene on chromosome 14 (101,044,198 to 101,044,283, forward strand). Ensembl gene ENSG00000221614.
Gene Ontology:
Biological process: miRNA-mediated post-transcriptional gene silencing
Cellular component: RISC complex
Homologues: Orthologues: chimpanzee ptr-mir-1185-2 (100% identical), dog MIR1185 (91% identical), macaque mml-mir-1185-1 (88% identical). Paralogues in human: MIR1185-1 (98% identical), MIR381 (65% identical), MIR539 (63% identical), MIR494 (62% identical), MIR487A (60% identical), MIR154 (59% identical), MIR323A (59% identical), MIR487B (59% identical), MIR323B (55% identical), MIR496 (55% identical), MIR410 (52% identical), MIR377 (51% identical), and 4 more.